CD44 (CD44 molecule (IN blood group))
Diseases named in the same sentence as CD44 in open-access papers (continued):
Sharing a sentence is not in itself a finding about the gene and the disease.
infection (continued). "As the infection continued, wild-type mice presented IFN-γ-producing (CD4+CD44+ and CD8+CD44+) T cells both in the spleen and heart while B2R−/− mice showed negligible frequencies of such activated T cells." (PMID 18052532, 2007). "Next, we adoptively transferred CD44+CD62L+GFI1hi, CD44+Ly108+GFI1hi or CD44+GFI1lo CD8+ T cells isolated from spleen and mLN of LCMVArm-infected mice at day 21 after infection into congenically marked secondary recipient mice that were subsequently infected with LCMVArm the next day." (PMID 40374731, 2025). "The results showed an increase in the proportion of stem cells in the S and G2/M phases, upregulation of proliferation-related genes, and activation of the Wnt pathway, evidenced by the elevated expression of Wnt target genes such as AXIN2, EPHB2, CCND1, CD44, TERT, and MYC following infection." (PMID 40396761, 2025). "To further understand the effects that anti-CD44 treatment had on the immune response to MA-10 infection, we analyzed the levels of 32 secreted cytokines and chemokines in the BALF of infected mice on day 4 post-infection." (PMID 41279061, 2025). "While the amounts of many other leukocytes increased with infection by varying degrees of significance, no other cell types were changed by anti-CD44 treatment." (PMID 41279061, 2025). "However, during microbial exposure or LCMV Armstrong infection, we show that CD8+ CD44+ and antigen-specific T cells from old mice have reduced degranulation, consistent with the diminished cytotoxic capacity." (PMID 40478430, 2025). "We demonstrated the presence of HC•HA in lung samples of MA10 SARS-CoV-2-infected mice on day 4 post-infection, indicating the formation of covalently modified HA had occurred in our model that was not affected by combined anti-CD44 antibody treatment." (PMID 41279061, 2025). "The titer of SARS-CoV-2 on day 4 post-infection was not significantly altered with treatment, indicating that the protection from pathology afforded by anti-CD44 treatment is the result of changes in the host immune response rather than reduced viral load." (PMID 41279061, 2025). "Interestingly, the use of a macropinocytosis inhibitor impaired both CD44 internalization and FMDV entry and infection, indicating a strong connection between these two processes." (PMID 40544280, 2025). "The frequencies of CD4+ CD44+ CD62L+ and CD8+ CD44+ CD62L+ presumed that central memory T cells were not altered in the lung by MBV treatment at day 21 after infection (P > 0.05)." (PMID 37205761, 2023). "Notably, at 12 days post-infection, we found a reduction of the frequency and number of CD8+ T cells activated (CD44+) producing granzyme B and perforin in the spleen of CKO mice compared to WT mice." (PMID 37908369, 2023). "Further analysis of CD44+CD4+ T cells in WT animals revealed FoxP3 expression was preferentially enhanced among CXCR5+ populations vs CXCR5- populations (15.40% ±1.93% vs 3.6 ±1.22) at two- and four-weeks post infection." (PMID 37721965, 2023). "While HylB promoted ascending GBS infection in wild-type (WT) and CD44-deficient mice, surprisingly, mice lacking both TLR2 and TLR4 (TLR2/4) were able to curtail these infections." (PMID 37747229, 2023). "When looking at specific subsets, we observed increased levels of CD44+CD62L- but not CD44+CD62L+ CD8+ T cells 9 days after infection." (PMID 37880206, 2023). "FoxP3 expression on CD44+CD4+ T cells was significantly decreased among μMT animals compared to WT at one- and two weeks post infection, suggesting B cells may drive TReg differentiation in response to Brucella." (PMID 37721965, 2023). "CD44 is also a marker of T cell activation, and similarly, significantly increased IFNγ+ and IL-17+ cells were present among CD4+CD44+ T cells from Mtb-HT1 infected mice at week 2 post infection." (PMID 35173157, 2022).
infection (continued). "BCGΔBCG1419c elicited T cell memory responses represented by the robust induction of antigen-specific polyfunctional effector memory CD4+/CD8+ CD44+CD62L- T cell responses before and after infection, and it especially induced CD8+ T cells more than BCG did prior to challenge." (PMID 36138053, 2022). "Activated CD44+ CD4 T cells initially expanded in the ILN and could be detected infiltrating the FRT during the first week of infection." (PMID 35196366, 2022). "Thus, the strategy of using the surface expression of CD44 and CD11a allows us to define the features of the polyclonal CD4 T cell responses to infection." (PMID 35215193, 2022). "As shown in the present study, the lack of DCIR contributes to a more effective priming of peripheral T cells with increased CD44 and reduced CD62L expression by CD4+ T cells together with an increased IFN-γ expression in the spleen during the early phase of TMEV infection." (PMID 34893671, 2021). "TIM-phenotype cells (CD44+CXCR3+CD49d+) are also seen after treatment with metformin, a drug used in treatment of type 2 diabetes, and they can contribute to increased protection against infection with M. Tuberculosis." (PMID 34398252, 2021). "Low titer CC-RIX mice with superior virologic containment at day 2 post-infection had a higher mean frequency of CD44+ CD4 and CD8 T cells in the spleen prior to infection, in addition to an increased proportion of CD4 T cells that express Ki67, which signals recent proliferation." (PMID 33513210, 2021). "Both SC and SIM mice showed an increase in both CD4 T cells and Cyt+CD44+CD4 T cells compared to mice that did not receive the second infection." (PMID 34925371, 2021). "To assess the phenotype of the responding γδ T cells of previously exposed mice after full resolution of infection, we stimulated spleen-derived γδ T cells from drug-treated mice or naïve mice in vitro and stained the cells for the surface markers CD62L and CD44." (PMID 33154754, 2020). "While the cytotoxic effector fraction (CD44+GzB+) decreased over time in both groups, only the LEC-educated cells showed a concomitant and significant increase in the TCM-like phenotype within 9 days post-infection." (PMID 31988323, 2020). "Therefore, we sorted virus-specific TFH cells and TH1 cells from the SMARTA chimeric mice on day 2 after the LCMV Armstrong infection and naïve CD4+ T cells (CD4+CD25−CD62L+CD44−) from naïve mice and subsequently performed H3K27me3 ChIP-Seq experiments." (PMID 30842630, 2020). "Together, the greater abundance of ITGAL, CD44, and CX3CR1 after calving suggested a potential greater influx and adhesion of leukocytes into tissues, likely contributing to decrease the incidence of infection postpartum." (PMID 32260288, 2020). "In mouse infection models, only PD-1int CD44+ but not PD-1hi CD44+ CD8 T cells were reinvigorated after PD-1/PD-L1 axis blockade." (PMID 32707692, 2020). "On the other hand, CD4+CD44+IFN-γ+IL-17+IL-2+ T-cells (R = −0.7133, p < 0.0001) and CD4+CD44+IFN-γ+TNF-α+IL-2+ T-cells (R = −0.6845, p < 0.0001) showed correlation with bacterial load only post-infection." (PMID 32545304, 2020). "The T-cell population was dominated by T-helper (Th) cells in noninoculated MEF, and the effector Th (CD44+) cell population increased at day 2 of NTHi infection with an increase in IL-12p40 levels." (PMID 31548315, 2019). "Intriguingly, even though both FRCs and HeLa cells express CD44, we observed that trans-infection is mediated by FRCs but not by HeLa cells." (PMID 29934525, 2018). "At 6 hrs after infection with L. monocytogenes the difference between CD44 positive and negative macrophages was most pronounced." (PMID 30540779, 2018). "Additionally, we found that the sphere size and number and the protein expression levels of CD44 and CD133 after LV-KRT23 infection were significantly increased compared with LV-NC in RKO cells." (PMID 28749462, 2017).
infection (continued). "In agreement with the gene expression analysis, at day 28 post-infection, the number of total CD8+ T cells as well as Mtb-specific CD8+ T cells (CD8+ CD44+ TB10.4+) in perigonadal fat increased while the number of CD4+ T cells remained unaltered in contrast to the lung." (PMID 29040326, 2017). "The data clearly showed that adding intranasal immunization to the parenteral immunization led to a strong post-infection increase in both the Th17 (CD4+CD44+IL-17+) and Th1 (CD4+CD44+IFNγ+) response as well the IgA response compared to the pre-infection response." (PMID 28414746, 2017). "On infection with PbA-infected red blood cells, both the percentage and the total number of CD8+ T cells, as well as PbA-specific H2-Db SQLLNAKYL pentamer+ CD44+ CD8+ T cells, were significantly increased in Cyld−/− mice at day 7 p.i.." (PMID 28203236, 2017). "For instance, CD69, CD160, CD44, LAG3, and CTLA-4 expression on day 7 is unaffected in the absence of AT1R following immunization, but here we showed that the expression of these proteins is reduced by day 6 following infection." (PMID 28261571, 2017). "While we detected small numbers of CD44+CD8+ memory T cells in the liver of OVA + BPPcysMPEG immunized mice following AdOVA-GFP-luc infection, these cells did not exert effector functions." (PMID 28266658, 2017). "In contrast, the relative proportions of CD44+ effector T cells in the MLN did not change substantially during the course of infection." (PMID 28615708, 2017). "Interestingly, after infection (43 dpi), a high proportion of antigen specific CD4+ T cells expressing CD44 and CD69 were observed in both NGP5B and NGP5B+CPG mice." (PMID 29069089, 2017). "To determine the effect of NK cell depletion on the frequency of activated/effector memory CD4+ T cells following secondary IOE infection, we measured the expression of CD62L and CD44 on T cells in the spleen of NK-/-EM/IOE and NK+/+EM/IOE mice 7 DPI after IOE infection." (PMID 27092553, 2016). "Additionally, mRNA levels of Gal-9, Tim-3, CD44, CD137, and PDI were significantly increased in the lungs at day 5 after infection, and the levels of CD137, IFN-α, IFN-β, IFN-γ, IL-4, and IL-10 in the lungs were also increased after α-lactose treatment." (PMID 27554340, 2016). "The conclusion that the memory T cells infiltrated the lung subsequent to infection rather than being tissue resident was supported by analysis of the number CD44+ T cells in tissue over time." (PMID 27300652, 2016). "The differential methylation of genes involved in memory T-cell responses, such as CD44, FOXO1 and FOXC1, might contribute to the inability of the host to mount responses capable of clearing infection." (PMID 27484700, 2016). "CD44 CD62L expression was low in infected control group (10.1%), which was up-regulated after treatment with AAL (13.8%) and AAS (15.1%) at 200 mg/kg b.w. demonstrating resolution of infection and generation of memory." (PMID 25568967, 2015). "Among CD44+ T cells, CX3CR1 expression was most prominent in CD8+ T cells, prompting us to study CX3CR1 expression on antigen-specific memory CD8+ T cells in response to infection." (PMID 26404698, 2015). "In general, all strains demonstrated an IFN-γ response by CD4+CD44+ and CD8+CD44+ cells to the crude M. leprae antigens (membrane, CWA, cytosol) and to ML2028 (Ag85B) at one or more points during long-term infection." (PMID 25210773, 2014). "We found that pre-existing, CD44+CD62L−T-bet+Ly6C+ effector (TEFF) cells that are short-lived in the absence of infection and are not derived from memory cells reactivated by secondary challenge, mediate concomitant immunity." (PMID 25473946, 2014). "Sorted populations of CD44+CD62L−Ly6C+, CD44+CD62L−Ly6C−, or CD44+CD62L+ TCM T cells from chronic animals were labeled with a proliferation dye and co-transferred with dye-labeled naïve CD62L+GFP+CD4+ cells from naïve mice into infection-matched recipients." (PMID 25473946, 2014).
infection (continued). "In contrast to the low number of CD44+CD62L−Ly6C+ cells found in naïve mice on day 14 post-transfer, substantial numbers of non-proliferated CD44+CD62L−Ly6C+ cells expressing Tbet were found 14 days following transfer into infection-matched recipients." (PMID 25473946, 2014). "FACS analysis using IM7 antibody showed that 47% of NPCs transduced with CD44-c-myc (thereafter named CD44-NPCs) express CD44 compared to only 7.3% in non-transduced NPCs (basal expression of CD44 in cells without infection thereafter named control NPCs)." (PMID 23468987, 2013). "To determine whether the T cells were activated following infection, we stained the T lymphocytes for the expression of the activation markers CD69, CD44/CD62L, CD40L." (PMID 23555767, 2013). "To study the cellular immune responses generated during Brucella infection we examined CD4+ and CD8+ T cell activation at several time points post-infection by measuring the surface expression of CD25, CD44 and the intracellular synthesis of effector molecules such as Granzyme B and IFN-γ." (PMID 24367519, 2013). "Moreover, the upregulation of the activated markers CD69, CD44, CD40L, and the downregulation of CD62L were observed in the CD4+ and CD8+ T cells following infection." (PMID 23555767, 2013). "During the course of infection, these peripheral DP cells acquire an activated phenotype similar to what is described for activated and memory single-positive T cells with high IFN-γ production, CD44+CD69+ expression, and cytotoxic activity." (PMID 22518275, 2012). "During the course of experimental infection, these peripheral DP cells acquire an activated phenotype similar to what is described for activated and memory single-positive T cells with high IFN-γ production, CD44+CD69+ expression and cytotoxic activity." (PMID 21858238, 2011). "In normal mammary tissue CD44+/CD24−/low stem cells TLR9 localized in endosomes in Ad5/3-Delta24 infected cells, as indicated by colocalization with an endosomal marker EEA1 and persisted still in the endosomes 6 h after infection." (PMID 21079774, 2010). "Interestingly, the synNotch proteins detected by the anti-CD44 antibody at 72 h after infection with CRAd-synNotch and ADX730 appeared to have lighter bands compared to the synthesized proteins at 24 h infection with CRAd-synNotch and 48 h infection with ADX730, respectively." (PMID 40011711, 2025). "Also, clusters rich in Cd44, indicative of T cell activation, Tbx21, highlighting the TH1-dominated immune response after LCMV infection, and Lag3, an early exhaustion marker, were only present after infection." (PMID 41094201, 2025). "Interestingly, we observed that activated (CD44+) CD4 T cells were significantly increased in frequency in aged mice compared to young mice on day 3 but not day 9 post-infection." (PMID 37852965, 2023). "Upon infection, aged mice failed to robustly increase CD44+ CD62L− T effector CD8+ T cells (TEM)." (PMID 37528458, 2023). "Instead, we hypothesized that most Nur77-GFPLO CD44+ CD4 T cell population are Mtb-specific effector cells expanded upon infection, but that have not recently been activated at the time of the harvest." (PMID 38110410, 2023). "CD63 is a tetraspanin family glycoprotein along with CD29 (integrin β1), CD44 (a multifunctional transmembrane receptor) (respectively), and LAMP (also known as CD107b), which were also found to be expressed and hence packaged within control and infection EVs derived from CCoV-infected CRFK cells." (PMID 36979955, 2023). "Consistent with what has been previously shown in in vivo infection models, the in vitro effector protocol generated cells that were CD44+CD62L-, while our optimized, low-avidity memory-inducing protocol mostly generated cells with the lymph node-resident CD44+CD62L+ phenotype." (PMID 35677061, 2022).
infection (continued). "Whether this difference, and the lack of differences in CD44, CD18, and Ly-6C that we observed in WT are responsible for the increased susceptibility to infection in KO mice remains to be determined." (PMID 35572576, 2022). "Regardless of CLR treatment, CFA+GLA-SE/CDG immunization significantly elicited Mav CFA-specific CD4+CD44+CD62 L− T cells producing IFN-γ+IL-17A+, and IFN-γ+TNF-α+ but not IFN-γ+IL-2+ in the lungs in the CFA+GLA-SE/CDG-immunized group compared with those in the infection control group." (PMID 35499090, 2022). "Regulatory T-cells (TREG, CD4+CD44+FoxP3+) ranged from 20% - 25% of activated CD4+ T-cells during UgCl223 infection and, unlike in lethal KN99α infections, were present at significantly lower levels compared to the predominant TH1 effector cell populations at all but the 0- and 77- day timepoints." (PMID 35186781, 2021). "However, the proportion of total CD4 T-cells and CD4+CD44+ activated T-cells out of total CD3+ T-cells did not change from 14- to 100- days post-infection." (PMID 35186781, 2021). "The expression of PD-1 on activated CD4+ T effector cells (CD3+CD4+CD44+CD62L−CD27−) and of PD-L1 on infiltrating monocytes (CD45+Ly6C+CD11b+) and resident macrophages (CD45+Ly6C−CD11b+F4/80+) were assessed in tissues from naïve WT mice and WT mice on days 12 and 35 post-infection (dpi)." (PMID 33193363, 2020). "However, after infection, we found that around 15% of the CD3+B220+CD117+ hepatic population became B220 and 7AAD negative, turned into CD90.2+, and upregulated the expression of CD44, CD49d, and CD11a, a phenotype consistent with activated T lymphocytes." (PMID 32878101, 2020). "Astrocyte heterogeneity revealed by differential CD44 upregulation occurs coincident with the earliest neuropathological changes during the pre-clinical phase of disease, and is not affected by the route of infection." (PMID 31551718, 2019). "In order to quantitate CD44 and CD74 expression at different subcellular localization across all conditions, MFI cross-sectional quantifications corresponding to the regions encompassing only the plasma membrane or the cytoplasm, both for CD74 and CD44, were performed in all infection conditions." (PMID 29997630, 2018). "However, complete deletion of CD44 does not limit the accumulation of CD8+ T cells at the site of initial infection, suggesting that this role is redundant when the cells can utilize other selectins expressed on the cell surface." (PMID 29632527, 2018). "Although we have not studied the memory response in the infection model here, we also found a significant lower percentage of cells expressing high levels of the CD44 activation/memory marker among CD4+ T cells lacking IL-1R expression, as well as among Myd88−/− and Il18r1−/−CD4+ T cells." (PMID 28895840, 2017). "The number of activated (CD44+), Myd88-/- vs. Myd88+/+ 1807 cells was not reduced at day 7 post-vaccination (burst of T cell expansion), at day 35 (contraction of T cells) and at day 4 post-infection (recall to the lung)." (PMID 27542117, 2016). "However, showed that CD44+CD62L-T-bet+Ly6C+ T- effector cells that are short-lived in the absence of infection and produce only IFN-γ play the key role in immunity against secondary infection by sandfly challenge." (PMID 27092123, 2016). "FACS analysis and real-time PCR results showed that the CD133+/CD44+ double-positive cell population increased or decreased after 5-Fu or CVV treatment, respectively, suggesting that CVV infection could kill stem cell-like HT29 cells more so that 5-Fu treatment." (PMID 26918725, 2016). "These parallels with CD44 raise the possibility that LYVE-1 could play a role in sensing HA complexes generated during inflammation in vivo, allowing the lymphatics to decode the status of interstitial matrix in injury or infection." (PMID 26823460, 2016).